FBN1 (fibrillin 1)
Diseases named in the same sentence as FBN1 in open-access papers (continued):
Sharing a sentence is not in itself a finding about the gene and the disease.
Pitt-Hopkins syndrome (1 paper, 2016). Pitt-Hopkins syndrome (PHS) is characterized by the association of intellectual deficit, characteristic facial dysmorphism and problems of abnormal and irregular breathing. "In four cases, patients’ phenotypes well matched to the syndromic features caused by haploinsufficiency of PAX6 (Aniridia, MIM:607108), TCF4 (Pitt-Hopkins syndrome, MIM:610954), FBN1 (skeletal/joint malformations, limb deformity; MIM:154700), and TWIST1 (Saethre-Chotzen syndrome, MIM:101400)." (PMID 27257017, 2016).
pituitary adenomas (1 paper, 2025). "Additionally, they proposed a potential role for matrix metalloproteinases, which are highly expressed in pituitary adenomas and may release growth factors anchored to the ECM, potentially degrading fibrillin-1 molecules and further contributing to ciliary apparatus weakness." (PMID 41220589, 2025).
polycystic ovary syndrome (1 paper, 2013). A disorder that manifests as multiple cysts on the ovaries. "In the recurrence subnetworks, DCN, THBS1, and THBS2 are members of the signaling KEGG pathway, and FBN1 controls the bioactivity of TGFs and relates to polycystic ovary syndrome." (PMID 23555212, 2013).
Pulmonary artery dilatation (1 paper, 2020). An abnormal widening of the diameter of the pulmonary artery. "In the comparison of the missense/in-frame variants with the nonsense/frameshift FBN1 variants, age of onset of pulmonary artery dilatation was earlier in patients with missense/in-frame FBN1 variants (p = 0.0334)." (PMID 32679894, 2020).
renal clear cell carcinoma (1 paper, 2023). "Furthermore, high expression of FBN1 is associated with poor survival outcome in renal clear cell carcinoma." (PMID 38269088, 2023). "In renal clear cell carcinoma, microarray analysis reveals that FBN1 induction is accompanied by a higher malignancy grade and progression." (PMID 38269088, 2023).
Stress urinary incontinence (1 paper, 2021). Involuntary urine leakage synchronous with exertion, or actions such as sneezing, or coughing. "A decreased gene expression and weaker immunoreactivity for fibrillin-1 was found in women with Stress Urinary Incontinence." (PMID 35026102, 2021).
Traboulsi syndrome (1 paper, 2021). "Although the role of FBN1 in Traboulsi syndrome was undefined, these studies suggested that the overlapped phenotypes may attribute to the molecular link between ASPH and FBN1." (PMID 33217155, 2021).
Turner syndrome (1 paper, 2025). Turner syndrome is a chromosomal disorder associated with the complete or partial absence of an X chromosome. "In the present study, a patient with mosaic Turner syndrome and the FBN1 variant c.6403G>A p.(Asp2135Asn) met the revised Ghent criteria with an aortic root Z-score of 7.93 and a systemic score of 7 points." (PMID 40169830, 2025).
viral encephalitis (1 paper, 2023). Encephalitis resulting from viral infection. "Patient #133 carried a heterozygous FBN1 mutation and presented with severely delayed bone age (BA-CA: -4 years) and additional phenotypic features, including viral encephalitis, sinus arrhythmia, and high arched palate." (PMID 37605180, 2023).
connective tissue disorder (142 papers, 2007 to 2025). A disease involving the connective tissue. "MFS is a connective tissue disorder caused by mutations in the gene that encodes the extracellular matrix (ECM) glycoprotein fibrillin-1." (PMID 40550200, 2025). "The fibrillinopathies, a diverse group of connective tissue disorders, are caused by pathogenic variants in FBN1 and FBN2 genes." (PMID 39273357, 2024). "These two similar syndromes are heritable connective tissue disorders in an autosomal dominant manner caused by mutations in two genes: FBN1 and FBN2, respectively." (PMID 37962692, 2024). "Upon conducting the genetic multipanel, we observed that in the group as a whole—comprising both those suspected of having MFS and other connective tissue disorders—the mutation in the FBN1 gene was present in 64 patients." (PMID 37688493, 2024). "Both collagen 1A1 (COL1A1) and fibrillin-1 (FBN1) are associated with connective tissue diseases, and the change in their expression aggravates vessel damage." (PMID 38715006, 2024). "MFS is one of the most common connective tissue disorders, caused by mutations in the extracellular matrix gene Fibrillin-1 (FBN1) (incidence 1:5000)." (PMID 38093926, 2023). "MFS is an inherited connective tissue disease caused by pathogenic variants in the Fibrillin-1 gene (FBN1), which codes for the ECM protein fibrillin-1." (PMID 34336739, 2021). "MFS is a connective tissue disease with autosomal dominant inheritance, originate from mutations of FBN1 encoding fibrillin-1." (PMID 34805315, 2021). "Since we also diagnosed other genes from Marfan-like diseases in addition to FBN1 variants, the actual detection rate of a causative gene mutation of a superordinate connective tissue disease is higher." (PMID 32679894, 2020). "MFS is a connective tissue disorder with an autosomal dominant inheritance due to pathogenic variants in FBN1 that encodes Fibrillin-1, a major element of the extracellular matrix, and connective tissue throughout the body." (PMID 29796325, 2018). "It is a connective tissue disorder with autosomal dominant associations in which the gene encoding for the fibrillin-1 (FBN-1) protein is affected." (PMID 29483877, 2018). "This information is highly relevant for understanding the underlying pathomechanisms of connective tissue disorders, such as Marfan syndrome, where an fibrillin-1-deficient matrix renders TGF-β PD-GF complexes unstable, resulting in aberrant TGF-β activation." (PMID 27059954, 2016). "This information is highly relevant for a better understanding of disease mechanisms driven by dysregulated GF activity as present in connective tissue disorders characterized by fibrillin-1 deficiency." (PMID 27059954, 2016). "Mutations in FBN1, the human gene encoding the fibrillin-1 isoform, are linked to several inherited connective tissue disorders." (PMID 23264024, 2014). "FBN1 mutations cause connective tissue disorder in terms of classic ocular, cardiovascular, and musculoskeletal abnormalities." (PMID 24093072, 2013). "MFS is a connective tissue disorder caused by mutations in the FBN1 gene, which codes for the extracellular glycoprotein fibrillin-1 that lead to Transforming Growth Factor β (TGF-β) signaling hyper-activation, vascular wall weakness and TAA onset at an early age." (PMID 39120283, 2024). "The pathophysiological importance of fibrillin-1 is highlighted by the linkage of heterozygous mutations in the fibrillin-1 (FBN1) gene (positioned on the long arm of chromosome 15) to a large family of connective tissue disorders known as type 1 fibrillinopathies." (PMID 37108724, 2023). "Several inherited connective tissue disorders (e.g., syndromes: Marfan, Ehlers-Danlos, Beals and Weill-Marchesani and osteogenesis imperfecta) that show clinical features of structural scoliosis were associated with rare mutations in FBN1." (PMID 35526034, 2022). "MFS is an inheritable connective tissue disorder caused by mutations in the FBN1 gene." (PMID 35895227, 2022).
connective tissue disorder (continued). "Given that, mutations in the human FBN1 gene are associated with connective tissue disorders." (PMID 33469097, 2021). "The proposed pathway is that SMAD4’s involvement in TGF-β signalling is shared with TGFBR1/2 and FBN1, genes involved in connective tissue disorders, where SMAD4 is a transcriptional regulator and tumour suppressor." (PMID 38066625, 2023). "FBN1, FBN2, and FBN3 encode the human fibrillins and mutations in FBN1 and FBN2 cause connective tissue disorders called fibrillinopathies, affecting cardiovascular, dermal, skeletal, and ocular tissues." (PMID 35910214, 2022). "MFS is a multisystem connective tissue disorder consisting of a defect in the microfibrillar protein fibrillin-1 gene (FBN1) on chromosome 15 (15q21.1)." (PMID 35692596, 2022). "MFS is a systemic disorder of connective tissues caused by pathogenic variants in the FBN1 gene, which encodes the major component of the extracellular matrix microfibril fibrillin-1." (PMID 33175881, 2020). "Mutations in human FBN1, FBN2, LTBP2, LTBP3 and LTBP4 have been associated with connective tissue disease in humans." (PMID 24703491, 2014). "Abnormal expression of FBN1 and its interactors have been reported before in heart diseases and in connective tissue diseases, providing an idea of their importance in those systems." (PMID 23951402, 2013). "Our findings expand the number of large FBN1 deletions, and emphasize the importance of screening for large genomic deletions in connective tissue disorders featuring aortopathies, especially for those with classic Marfan phenotype." (PMID 21936929, 2011). "Mutations in FBN1 and FBN2 cause connective tissue disorders called fibrillinopathies." (PMID 35910214, 2022). "While genetic testing for the FBN1 gene, as suggested by the Ghent criteria, improves the likelihood of diagnosing MFS, it is insufficient for ruling out other Marfan-like connective tissue disorders." (PMID 37688493, 2024). "We aimed to investigate qualitative and quantitative effects of 16 mutations in FBN1 on FBN1 mRNA in cultured fibroblasts from 16 MFS patients, comparing with fibroblasts from individuals with no known connective tissue disorder." (PMID 26684006, 2015). "We observed high inter-individual variability in FBN1 expression levels in fibroblasts from individuals with no connective tissue disorder, as well as in MFS patients, similar to results reported by other investigators." (PMID 26684006, 2015). "This study was motivated by two other recent studies that suggested FBN1 alterations in DS which is usually downregulated in MFS, MFS-like and in other connective tissues disorders like Williams–Beuren syndrome." (PMID 23951402, 2013).
tumor (58 papers, 2004 to 2025). "Supporting this, CXCR7 levels positively correlated with classic ECM and reactive stromal cell markers, including FBN1 which is strongly associated with OC tumor staging and poor overall survival." (PMID 30051594, 2018). "FBN1, a risk factor according to our analysis, has been shown by previous research to be positively correlated with carcinogenesis, as well as with a higher risk of tumor development in a pan-cancer analysis based on a million-case Taiwan cohort." (PMID 36091054, 2022). "The top 6 most abundant proteins encoded by COL6A1/2/3, COL1A1/2, and FBN1 detected in both NAT and tumor tissues and exhibited a similar trend in both composition and abundance." (PMID 40032993, 2025). "HEYL, SLC2A3, and FBN1 were found to mediate tumor progression and chemoresistance mainly by facilitating angiogenesis and EMT, while CERCAM, ANXA1, and SPOCD1 promoted tumor progression through the PI3K/AKT and EGFR signaling pathways." (PMID 39033778, 2024). "Upregulation of CPT1A and downregulation of SIRT5 synergistically promotes S100A10-K47succ and fibrillin 1 (FBN1) K672succ, resulting in the accumulation of S100A10 and FBN1 in GC cells and further promoting tumor progression." (PMID 38882606, 2024). "Under pathological conditions, dysregulated FBN1 can promote the proliferation of tumor cells or induce apoptosis in endothelial cells." (PMID 38269088, 2023). "Particularly, FBN1 is often upregulated in a variety of cancers and has been proposed as a promising tumor biomarker." (PMID 38269088, 2023). "The matrix metalloproteinase 2 (MMP2) can degrade FBN1, but succinylation of FBN1 on K672 disrupts this interaction with MMP2 in the tumour microenvironment causing an accumulation of FBN1." (PMID 38213532, 2023). "Our bioinformatic analysis demonstrated a remarkable difference in FBN1 expression among multiple tumor types." (PMID 35901491, 2022). "Previous investigations showed that versions, the vast extracellular proteoglycan matrix, were found in conjunction with fibrillin-1, which played a critical role in tumor invasion and metastasis." (PMID 35356627, 2022). "In the 3D matrix invasion and zebrafish experiments we found that antibodies against the K672 site of FBN1 effectively inhibited tumor invasion and proliferation." (PMID 35901491, 2022). "Together, these results suggest that FBN1 promotes GC cell proliferation, and our FBN1‐K672suc monoclonal antibody is a promising tumor proliferation intervention tool." (PMID 35901491, 2022). "The long‐term accumulation and deposition of FBN1 enhance tumor progression by activating TGF‐β1 and intracellular PI3K/Akt pathway." (PMID 35901491, 2022). "Our bioinformatic analysis identified a relationship between FBN1 expression and tumor proliferation, and the PI3K/Akt signaling pathway." (PMID 35901491, 2022). "The preference of the FBN1 expression in fibroblasts was confirm in a single cell RNA set (GSE118828) downloaded from the Tumor Immune Single-cell Hub (TISCH)." (PMID 36119108, 2022). "Subsequently, the MKN45–CAF co‐culture system was applied to the zebrafish cell line‐derived xenograft model to better illustrate the relationship between FBN1 and tumor proliferation." (PMID 35901491, 2022). "We also performed a plate cloning assay in the same co‐culture system to directly confirm that FBN1 promotes tumor cell proliferation." (PMID 35901491, 2022). "In summary, the expression level of the FBN1 substructure is more sensitive for judging tumor prognosis than the pan‐FBN1 expression level." (PMID 35901491, 2022). "We identified all cysteine mutations showing a plasma cell tumor phenotype in each potential binding partner (LTBP1–4, FBN1–3, LRC32/33, and SELE)." (PMID 36214621, 2022). "Several lines of evidence indicate that FBN1 down-regulates the growth and sprouting of tumor endothelial cells via promoter histone modifications." (PMID 32595417, 2020).
tumor (continued). "Another study revealed, that FBN-1 expression is stimulated by Aurora A, a serine/treonine kinase, and is inhibited by tumour suppressor gene BRCA2." (PMID 27487789, 2016). "This included EC-specific proteins (e.g. COL1A1, FBN1), tumour-specific proteins (e.g. ITGB1) and proteins up-regulated in both cell types (FN1, THSB1, CD44, ITGA4, CTGF)." (PMID 27049916, 2016). "For FBN1, methylation was found in 77.5% (69/89) of tumor tissue samples and 3.4% (3/89) of normal mucosa." (PMID 25802477, 2015). "The mechanical interaction between the accumulated FBN1 and integrins β3 and β5 on the tumor cell surface resulted in the separation of TGF‐β1 from the latency‐associated peptide complex, activating TGF‐β1 and triggering the PI3K/Akt signaling pathway, thereby promoting tumor proliferation." (PMID 35901491, 2022). "Furthermore, we analyzed 32 tumor types prognostically, finding that the hazard ratio (HR) of patients with GC expressing FBN1 was as high as 1.21, which ranked higher on a scale." (PMID 35901491, 2022). "To verify whether succinylated FBN1 could predict tumor prognosis, we performed a tissue microarray analysis that included approximately 150 patients using an FBN1‐K672suc monoclonal antibody." (PMID 35901491, 2022). "Interestingly, tumor cell proliferation decreased considerably in the group treated with the anti‐FBN1‐K672suc monoclonal antibody." (PMID 35901491, 2022). "Transcriptomic profile analysis showed that two genes (L1CAM and FBN1) were upregulated and that four genes (AUST2, MAPT, AGT and USH1C) and two microRNAs (hsa-mir-100 and hsa-mir-378) were downregulated, all of which were associated with tumor malignancy." (PMID 29215599, 2017). "In fact, nearly complete ablation of FN by ROSA-CreER-mediated global deletion does not significantly impede tumor angiogenesis, deposition of basement membrane proteins, or recruitment of matrix-linked proteins Fibrillin-1 and -2." (PMID 25807551, 2015). "Here we found that the DNA methylation of CNRIP1, FBN1, INA, and SNCA was associated with reduced or lost gene expression in cell lines, indicating that they might harbor a tumor suppressor function." (PMID 21777459, 2011). "Furthermore, ECM components, such as collagen isoforms, Fibrillin-1, EMILIN-1, Prolargin, and Lumican, were found to be highly expressed in the MLH1/PMS2-deficient tumor area, suggesting a connection between DNA repair deficiencies, ECM remodeling, and tumor progression." (PMID 40076915, 2025). "Therefore, in GC with highly succinylated FBN1 expression, we hypothesize that extracellular components allow tumor cells to increase the Akt activation signals, resulting in tumor proliferation." (PMID 35901491, 2022). "Furthermore, the activity of Insulin like Growth Factor Binding Protein 4 (IGFBP4), which was also highly expressed in ES and ES-CSCs, is regulated by proteins of the tumour microenvironment which may include fibrillin-1." (PMID 34403115, 2021). "Furthermore, SPARC, COL6A3, and FBN1 play an important role in tumor-related immune infiltration and may be ideal targets for immune therapy against PDAC." (PMID 32934754, 2020). "Consequently, the FBN1 gene can be considered as a potential tumor suppressor and its down-regulation could play a role in tumor angiogenesis." (PMID 28067804, 2017). "The presence of fibrillin-1 alone along sinusoids was discontinuous, irregular and some areas were completely unstained; on the contrary, peliotic zones showed a more intense staining than the non-peliotic ones, but this staining was irregularly distributed within the tumor." (PMID 14960209, 2004). "MMP2 overexpression is from transcription of HIF-1, and FBN1 buildup can increase the level of HIF-1 and induce MMP2 expression, leading to tumor cell invasion into matrix." (PMID 40865948, 2025).